FBLN1 (fibulin 1)
Diseases named in the same sentence as FBLN1 in open-access papers (continued):
Sharing a sentence is not in itself a finding about the gene and the disease.
cancer (39 papers, 2003 to 2025). A tumor composed of atypical neoplastic, often pleomorphic cells that invade other tissues. "As the disease advanced, Fib_FBLN1+ fibroblasts—associated with tissue repair and homeostasis gradually transitioned into cancer-associated fibroblasts (CAFs), including Fib_POSTN+, Fib_CD74+, and Fib_CXCR4+ subpopulations." (PMID 40948762, 2025). "On the other hand, fibrin-1 expression in the cancer microenvironment of PC was associated with prognosis, and the survival rate was significantly lower in the high fibulin-1 expression group than in the low fibulin-1 expression group." (PMID 41301725, 2025). "FBLN1 has also been implicated in the development of various cancers." (PMID 39201719, 2024). "In addition, we observed FBLN1 encoding the basement membrane component Fibulin-1 to be strongly downregulated in 'both' cancers, and in cancers overall." (PMID 17280610, 2007). "Besides the reported NSCLC candidate markers, we found sizeable noteworthy proteins closely related to other cancers, such as alpha-1B-glycoprotein, Complement C1q subcomponent subunit A, fibrinogen alpha/gamma chain, fibulin-1, platelet factor 4 and its variant." (PMID 23284758, 2012). "Beyond pregnancy, FBLN1 has been proposed as a biomarker of vascular and tissue remodeling in renal disease and cancer." (PMID 41614738, 2025). "FBLN1 has a critical role in epithelial-to-mesenchymal transition (EMT) during cancer due to its capability of regulating cell differentiation, adhesion, migration, and proliferation." (PMID 37719007, 2023). "Studies have shown that FBLN1 can regulate cell morphology, adhesion, spread and promote cell movement, which is related to cancer growth, cell migration, and invasive growth." (PMID 35217799, 2022). "Inhibition of Fibulin-1 sensitized cancers cells to apoptotic signals, suggesting that FBLN1 serves a protective role from cell apoptosis." (PMID 36176297, 2022). "FBLN1 can bind to target proteins (fibronectin, fibrinogen, angiopoietin, laminin-1, etc.)to inhibit the signal transduction, cancer cell growth, migration, and invasion." (PMID 35127942, 2022). "Fibulin-1, which is expressed mainly by cancer cells and only by some fibroblasts, has been reported to be overexpressed in lymph node biopsies from HL patients." (PMID 32235718, 2020). "Although abnormal Fibulin-1 expression is frequently observed in different types of cancer, the biological function of dysregulated Fiublin-1 expression is largely cell context-dependent." (PMID 32612994, 2020). "As shown in the present study, Fibulin-1 silencing in the different cancer cell lines promoted apoptosis." (PMID 32612994, 2020). "A majority of these genes had been described in different cancers, including FBLN1 or INHBA, but only a few in CRC." (PMID 24516561, 2014). "Fibulin 1 can interact with HPV E6 including cancer-related HPV E6s and the transforming bovine papillomavirus 1 (BPV1) E6." (PMID 18985039, 2008). "In addition, TCGA database analysis focused on other types of cancers showed that the expression of fibulin-1 in cancer patients tended to be decreased." (PMID 41301725, 2025). "Fibulin-1 (FBLN1) is involved in the progression of some types of cancer." (PMID 25837757, 2015). "The EdU detection confirmed that re-expression of fibulin-1 could effectively inhibit cancer cell proliferation (P < 0.05)." (PMID 25234557, 2014). "Interestingly, the expression of fibulin-1 in cancer cell lines was a little different with tissue samples." (PMID 25234557, 2014). "Interestingly, several of these small and large altered regions contain cancer-associated genes known to be involved in CRC and/or the metastatic process: i.e. the TPD52, FABP5, MAP2K4, LLGL1, FBLN1 and TYMP genes." (PMID 21060790, 2010). "Moreover, SPOCK1 expression was significantly elevated (p = 0.002) in ERG-high cancers and that of FBLN1 was significantly diminished (p = 0.047)." (PMID 20860828, 2010).
cancer (continued). "Evidence supporting a role for CXCL1 in CRC pathology was recently provided by a study demonstrating an association between increased expression of CXCL1 and down-regulation of the matrix protein fibulin-1, which is known to suppress the motility of various cancer cells." (PMID 18578857, 2008). "In these cancers, FBLN1 becomes upregulated during progression." (PMID 17280610, 2007). "Therefore, we analyzed whether Fibulin-1 affected the apoptosis of cancer cells grown in nutrient-deprived medium." (PMID 32612994, 2020). "Thus, the role of fibulin-1 in cancer progression may vary with cancer type." (PMID 37719007, 2023). "Of the four known FBLN1 isoforms relative expression of FBLN1C and 1D, known to be ubiquitously expressed, were tested across a panel of cancer cell lines by quantitative RTPCR and were found to be comparable." (PMID 32719793, 2020). "In CALU downregulated cancer types, the CALU-1/− 2 / fibulin-1 complex bound to fibronectin and inhibited ERK-1/2 signalling and cell migration in an integrin- and syndecan-dependent manner." (PMID 31118065, 2019). "Ingenuity analysis identified a group of 7 genes (BEX1, FBLN1, FGD3, HBEGF, KLK3, KLK6, and WNT5B) related to cancer, cellular function and maintenance, cellular growth, invasion, as well as proliferation with P < 0.001-0.05." (PMID 21134280, 2010). "In addition, several genes that were reported to be related to a less cancer aggressiveness or metastatic potential were found to be increased upon PAGE4 overexpression, including ACTA2, FBLN1 and F2R." (PMID 30658679, 2019). "Fibulin-1(Fbln-1) is a member of an emerging family of glycoproteins found in extracellular matrix (ECM) and blood and has been observed to inhibit in vitro adhesion and motility of various carcinoma cell lines." (PMID 21113302, 2010).
cardiovascular disease (10 papers, 2012 to 2024). "We aimed to define the relationship between plasma fibulin-1 levels and risk markers of cardiovascular disease." (PMID 23294625, 2013). "The exact role of fibulin-1 in cardiovascular disease may be complex since it is associated with pathologies in both, arterial and heart tissue." (PMID 23294625, 2013). "Besides being an ECM protein, fibulin-1 circulates in high concentrations in plasma and is a cardiovascular disease biomarker reflecting elastolysis." (PMID 29867203, 2018). "These associations of plasma fibulin-1 are compatible with the idea that fibulin-1 may have a role in the complex pathogenesis of cardiovascular disease." (PMID 23294625, 2013). "Based on these findings fibulin-1 may be involved in the development or progression of cardiovascular disease." (PMID 23294625, 2013). "The extracellular matrix protein fibulin-1 is emerging as a new factor in cardiovascular disease." (PMID 23294625, 2013). "Nevertheless, the proof of a cause-effect relation between cardiovascular disease in humans and osteoprotegerin or fibulin-1 is still lacking and the role of both proteins for diagnosis or assessment of progression of cardiovascular disease awaits further study." (PMID 23294625, 2013). "Moreover, we aimed to evaluate the significance of MFAP4 as a marker of cardiovascular disease (CVD) and to correlate MFAP4 with other known ECM markers, such as fibulin-1, osteoprotegerin (OPG), and osteopontin (OPN)." (PMID 24349233, 2013).
kidney disease (6 papers, 2013 to 2025). "The genes UPK3A, FBLN1, WNT7B, and CELSR1 have the strongest evidence of association with kidney disorders." (PMID 35741804, 2022). "The results from this study suggest that UPK3A, FBLN1, WNT7B, and CELSR1 are strong candidate genes for kidney disorders in PMS and merit functional studies." (PMID 35741804, 2022). "Using association analysis, candidate gene prioritization based upon a set of known kidney-related genes and estimates of haploinsufficiency, we identified UPK3A, FBLN1, WNT7B, and CELSR1 as priority candidate genes for kidney disorders." (PMID 35741804, 2022).
infection (3 papers, 2024 to 2025). The state of being infected such as from the introduction of a foreign agent such as serum, vaccine, antigenic substance or organism. "Fibulin-1 and laminin were also highly increased post-infection." (PMID 38803570, 2024).
respiratory diseases (2 papers, 2024). "Given the emerging role of FBLN1 in regulating ferroptosis and its impact on respiratory diseases, this research intended to explore the potential guarding impacts of FBLN1 overexpression against lipopolysaccharide (LPS)-induced ARDS." (PMID 39671383, 2024).
cardiac disease (1 paper, 2014). "Up regulation of fibulin-1 is associated with cardiac disease, while up regulation of fibulin-2 and fibulin-3, although not implicated in cardiac disease, is associated with a variety of other fibrotic disorders." (PMID 25117565, 2014).
connective tissue disorder (1 paper, 2013). A disease involving the connective tissue. "Other networks significantly enriched also related to a further network in connective tissue disorders that contained genes including collagens COL10A1, COL11A1 and COL2A1 plus a disintegrin and metalloproteinase with thrombospondin motifs-2 (ADAMTS-2) and fibulin-1 (FBLN1)." (PMID 23971731, 2013).
neurodegenerative disease (1 paper, 2024). A disorder of the central nervous system characterized by gradual and progressive loss of neural tissue and neurologic function. "Previous studies have confirmed the association of FBLN1 with neurodegenerative diseases, but there are no reports on the methylation modifications of FBLN1 in hippocampal tissue." (PMID 39201719, 2024).
FBLN1 also shares sentences with these, for which no sentence is quoted: Alzheimer disease (2 papers); amyloid (2); cardiac hypertrophy (2); chronic asthma (2); cognitive deficits (2); epidermoid carcinoma (2); Hypertension (2); idiopathic pulmonary fibrosis (2); acute respiratory distress syndrome (1); adenocarcinoma (1); age-related macular degeneration (1); aortic aneurysm (1); arterial disease (1); autism spectrum disorder (1); bacterial infection (1); benign tumours (1); biliary atresia (1); bipolar disorder (1); bladder transitional cell carcinoma (1); cholangiocarcinoma (1); colon cancer (1); coronary heart disease (1); COVID-19 (1); craniosynostosis (1); Ehlers-Danlos syndrome (1); end-stage renal disease (1); epilepsy (1); fracture (1); genetic disorders (1); hemorrhage (1).
A further 41 diseases each share a sentence with FBLN1 in 1 paper.